IL6 (interleukin 6)
Diseases named in the same sentence as IL6 in open-access papers (continued):
Sharing a sentence is not in itself a finding about the gene and the disease.
sarcoma (33 papers, 1995 to 2025). A usually aggressive malignant neoplasm of the soft tissue or bone. "Consistent with the opposing effects of EWS/ATF1 expression on senescence, Il-6, a senescence-associated secretory phenotype-associated gene was inversely regulated in sarcoma cells and sarcoma-iPSC MEFs." (PMID 31488818, 2019). "Loss of IL-6 in the ∆122/+ mice resulted in a decreased incidence of T-cell lymphomas as well as a significant reduction in sarcomas that underwent metastasis." (PMID 29343721, 2018). "For example, IL6 is a risk gene in multiple cancers but plays a protective in only sarcoma (SARC)." (PMID 35246158, 2022). "IL-6/STAT3 is an essential pathway involved in the progression of metastatic sarcoma, and IL-6 production via sarcoma exosomes made mesenchymal stem cells responsible for stimulating sarcoma metastasis." (PMID 36979391, 2023). "On the other hand, IL6 expression represented a favorable prognostic indicator only in sarcoma patients." (PMID 34576335, 2021). "It was recently reported that CD163-positive macrophages are also associated with both proliferation in Saos-2 cells and tumor progression in a sarcoma-bearing mouse model by IL-6-induced STAT3 activation." (PMID 32256354, 2020). "Most tumours in Δ122/Δ122 IL-6+/− mice were either T-cell lymphomas (56%, 5/9) or sarcomas (22%, 2/9), however, 1 mouse had co-existing malignancies." (PMID 29343721, 2018). "For sarcomas, 5/13 of Δ122/+ IL-6+/+ mice showed evidence of metastases involving multiple organs while only 1/16 Δ122/+ IL-6+/− mice showed evidence of metastases involving multiple organs." (PMID 29343721, 2018). "The majority of Δ122/Δ122 IL-6+/+ mice had either T-cell lymphomas (64%, 18/28) or sarcomas (14%, 4/28), although 3 mice had co-existing malignancies, and 1 mouse had a localised B-cell lymphoma." (PMID 29343721, 2018). "We used a panel of EwS, RMS and OS pediatric sarcoma cell lines to test six cytokines, used for monocyte differentiation and DC maturation (IL-4, GM-CSF, IL-1β, IL-6, TNF and PGE2), for their ability to induce cancer cell immunogenicity and sensitivity to tumor antigen-specific T cells." (PMID 39723214, 2024). "Another scenario in which a role for ERK5 in sarcomas could be envisaged relates to the inflammatory cytokine IL-6." (PMID 37332046, 2023). "For heterozygous Δ122/+ IL-6+/− mice, 50% (13/26) had sarcomas alone and 1 mouse had a carcinoma." (PMID 29343721, 2018). "Likewise in human patients and mouse models, prior studies evaluating the NF-λB/IL-6/STAT3 axis in other types of sarcoma have reported increased IL-6 signaling and attenuation of tumorigenesis following treatment with IL-6 inhibitors." (PMID 27105514, 2016). "Since tumor-associated macrophages express higher concentrations of cytokines including IL-6, increased IL-6 may be one mechanism that leads to aberrant activation of JAK/STAT3 pathway in pediatric sarcomas." (PMID 23531921, 2013). "Tumor necrosis factor alpha (TNFα) has been examined both as an additive to HILP with melphalan in sarcoma surgery, and also its effects on the formation of cytokines such as interleukin 6 and interleukin 8, the latter being more pronounced when TNFα was added for therapeutic purposes." (PMID 23865420, 2013). "So, blocking IL-6/STAT3 may be an excellent approach used to suppress sarcoma metastasis." (PMID 36979391, 2023). "In contrast to TNF and IL-1β, the other tested monocyte maturation mediators, including IL-4, GM-CSF, IL-6 and PGE2, weakly affected expression of immunogenic surface markers on pediatric sarcoma cells." (PMID 39723214, 2024). "JNK/p38-MAPK, PVT1/ERG, programmed cell death 4 (PDCD4)/ERK1/2, SOCS3/JAK2/STAT3, TGF-β/COL6A1, IL6/STAT3, PI3K/Akt/mTOR, and Hedgehog in exosomes regulate genes or signaling pathways to promote the migration and metastasis of sarcoma cells." (PMID 36979391, 2023). "In this subtype of sarcoma, CDKN2A firmly connects to MDM2, CCND1, PIK3CA, CDK4, CBX7, and less firmly to EGFR, and IL-6." (PMID 34359782, 2021).
sarcoma (continued). "ISG15 and IF16 are directly linked together but through PCNA and then through CCND1 they connect indirectly to the common to all sarcomas’ major hubs FGF2 and IL-6." (PMID 34359782, 2021). "CD163 promotes murine sarcoma progression by inducing IL-6 secretion, which indicates the pro-tumorigenic role of TAMs expressing CD163 in sarcoma." (PMID 32256354, 2020). "Interestingly, and somewhat paradoxically given our serum ELISA and tumor tissue PCR results, we observed that higher expression of IL-6 (HR 0.46, 95% CI 0.26–0.82, P = 0.007) and the IL-6 receptor/CD126 (HR 0.46, 95% CI 0.27–0.79, P = 0.004) were both associated with greater OS in human sarcomas." (PMID 32084139, 2020). "A recent study revealed that CD163+ TAMs promoted expression of IL-6 and CXCL2 by cancer cells while inhibition of either IL-6 or CD163 macrophage-induced tumorigenesis in a co-culture in vitro system and a sarcoma mouse model." (PMID 32509781, 2020). "Consistently, Cdkn1a and Ink4a, as well as Il-6, were upregulated in Ebf1-KRAB-expressing sarcoma cells when compared with control NANOG-KRAB-expressing sarcoma cells." (PMID 31488818, 2019). "IGF1R CAR T cells produced higher amounts of IL-6 and IL-18 than ROR1 CAR T cells in response to certain sarcoma lines." (PMID 26173023, 2015). "Levels of IL-1β, IL-4, IL-6, CXCL5, CXCL12, CXCL14, MIF, IGF-1, TGFβ-1, and CCL21 were increased in one or more sarcoma cohorts compared with controls, and levels of IL-15 and IL-16 were significantly lower in one or more sarcoma cohorts compared to healthy controls." (PMID 41008853, 2025). "We observed that TNF and IL-1β upregulated MHC class I, ICAM-1 as well as CD83 and PD-L1 on the surface of pediatric sarcoma cell lines, while IL-4, GM-CSF, IL-6 and PGE2 failed to induce respective effects." (PMID 39723214, 2024). "While sarcomas exhibit the tumor-promoting effects of CCL18 and IL-6, the impact of other cytokines remains unclear." (PMID 38302407, 2024). "Despite expression of IL-6R and IL-6ST on EwS cell lines, IL-6 did not modulate expression of immunogenic markers on pediatric sarcoma cell lines." (PMID 39723214, 2024). "For Δ122/Δ122 IL-6−/− mice the incidence of T-cell lymphomas decreased to 53% (10/19), and 21% (4/19) had sarcomas; and there were no co-existing tumours." (PMID 29343721, 2018). "On the other hand, mmu-mir-140 depletion in Rb intact sarcoma cells was not sufficient to induce robust Il-6 upregulation or increased sphere forming activity (data not shown), suggesting that mmu-mir-140 mediates Rb function to suppress Il-6 and sphere formation in a limited degree." (PMID 28099924, 2017).
amyotrophic lateral sclerosis (32 papers, 2012 to 2025). Amyotrophic lateral sclerosis (ALS) is a neurodegenerative disease characterized by progressive muscular paralysis reflecting degeneration of motor neurons in the primary motor cortex, corticospinal tracts, brainstem and spinal cord. "Treatment with violacein significantly decreased pro-inflammatory cytokines such as TNF-α, IL-1β, and IL-6 in the spinal cord of rats with amyotrophic lateral sclerosis (ALS)." (PMID 40430892, 2025). "Although the role of IL-6 in neuromuscular pathologies is not fully understood, elevated IL-6 levels have been used as a disease progression biomarker in certain groups of amyotrophic lateral sclerosis (ALS) patients, specifically those with the IL6R358Ala variant." (PMID 39796228, 2025). "IL-6 is involved in the pathogenesis of amyotrophic lateral sclerosis, a pathologic condition where P-gp activity is increased." (PMID 36882782, 2023). "The proinflammatory cytokines/chemokines IL-6 and IL-8 are among the inflammatory responses associated with various neurological disorders including Parkinson's disease, Alzheimer's disease, and amyotrophic lateral sclerosis (ALS)." (PMID 22420994, 2012). "With respect to amyotrophic lateral sclerosis (ALS), significantly higher blood levels of IL‐1β, IL‐6, IL‐8, TNF‐α, TNF receptor 1 (TNFR1), and vascular endothelial growth factor (VEGF) were found in the disease condition compared to the control group." (PMID 40709483, 2025). "Notably, in vivo pharmacological inhibition of IL-6 effectively counteracts denervation-mediated muscle atrophy and accumulation of FAPs with hyper-activation of IL-6 signaling has also been found in mouse models of amyotrophic lateral sclerosis (ALS)." (PMID 31496956, 2019). "IL-6/STAT3 signaling inactivation in FAPs counteracted muscle atrophy and fibrosis in mouse models of acute denervation and amyotrophic lateral sclerosis (ALS)." (PMID 31114509, 2019). "For example, the assumption that systemic overexpression of IL-6 may contribute to BBB failure and the development of amyotrophic lateral sclerosis has been formulated." (PMID 30428632, 2018). "Conditioned medium from bone marrow derived stem cells (BMSCs-CM) was reported to markedly reduce the expression of IL-6, iNOS and TNF-α in astrocytes cells derived from amyotrophic lateral sclerosis (ALS) transgenic mice." (PMID 31024252, 2019). "In a study analyzing amyotrophic lateral sclerosis (ALS) blood cells, which normally secrete TNF-α and IL-6, researchers found that these cells were toxic to rat neurons in vitro." (PMID 29167670, 2017). "Additionally, one recent study found simulation of lymphocytes with a HERV-K env peptide significantly upregulated expression of IL-6 in patients with amyotrophic lateral sclerosis (ALS) but not in healthy controls." (PMID 35711940, 2022).
mental disorder (32 papers, 2011 to 2025). A disease that has its basis in the disruption of mental process. "We previously reported that individuals with a history of childhood abuse, a significant risk factor for developing stress-related mental disorders, exhibit a diminished salivary IL-6 diurnal rhythm." (PMID 37324818, 2023). "Above all, disrupted IL-6 secretion has been commonly observed and thus conceivably underlies the pathophysiology of stress-related mental disorders." (PMID 37324818, 2023). "Future longitudinal studies should seek to include repeat measures of childhood IL-6 to examine effects of persistent inflammation, elevated IL-6 particularly, on the risk of adult mental disorders." (PMID 33684738, 2021). "However, accumulating evidence suggests that mental disorders are associated with elevated levels of inflammatory biomarkers, such as interleukin-6 (IL-6), tumor necrosis factor-alpha (TNF-α), and C-reactive protein (CRP)." (PMID 41019538, 2025). "Thus, alterations in the diurnal patterns and total output of IL-6 may be the key factors underlying one’s vulnerability to stress-related mental disorders, through gene-stressor interactions." (PMID 37324818, 2023). "A meta-analysis revealed considerably higher concentrations of IL-1β and IL-6 in blood and postmortem brain samples of individuals with mental disorders who had attempted suicide." (PMID 41035953, 2025). "Disrupted interleukin-6 secretion and aberrant amygdala emotional reactivity are well-documented in stress-related mental disorders." (PMID 37324818, 2023). "IL-6/STAT3 pathway has been reported to be involved in chronic pain and mental disorder, so we tested the role of IL-6/STAT3 pathway in the SNI-induced comorbid-like behavior in rats." (PMID 35690777, 2022). "As known that MDD is a mental disorder that originates from brain dysfunction, we measured the peripheral level of IL6 mRNA expression in this study." (PMID 27502736, 2016). "Inflammatory factors, such as IL-6 and CRP, may also have the potential to serve as early warning indicators for air pollution-related risk of mental disorders." (PMID 39058106, 2024). "Developing an understanding of this blunted diurnal IL-6 rhythm, a possible precipitant in stress-related mental disorders such as MDD, is expected to facilitate their early detection, prevention, and treatment such as pharmacotherapy to ameliorate the disrupted secretion of inflammatory markers." (PMID 37324818, 2023). "Also, cytokines like IL-1β and IL-6 were detected at statistically significant levels in the cardiovascular disease group and all cytokines included in this study were quantified in the mental disorders group." (PMID 39328992, 2024). "Compared to common cytokines like INF-γ, IL-6, and TNF-a, NLRP3 and IL-18 have rarely been studied in clinical studies of mental disorders." (PMID 38627683, 2024). "For Mental Disorders, the path with the strongest literature backing (i.e., total number of publications) was the one linking TGFB1 with this disease group via IL-6, both genes co-expressed in the cerebral cortex." (PMID 35360842, 2022). "Subsequently, we examined how immune-mediated classes were reflected in leukocyte counts, inflammatory markers (IL-1β, IL-6, TNF-α, hsCRP), chronic inflammatory diseases, and mental disorders, and how they differed across social classes and birth cohorts." (PMID 30961604, 2019). "Therefore, further research to understand and compare the potential distinct role of IL‐6 and CRP in the development of mental disorders is needed." (PMID 36597271, 2023). "Although casualty has not been proven, high C-reactive protein (CRP) and interleukin 6 (IL-6) concentration are reported in mental disorders." (PMID 34465310, 2021). "A meta-analysis also suggested IL-6 and TNF-α may play a negative role in the pathogenesis of mental disorders." (PMID 36465283, 2022).
mental disorder (continued). "Our review suggests that several oxidative stress and inflammatory biomarkers, such as peripheral TAC, IL-17, IL-6, and CRP, may be possible non-specific early warning indicators for air pollution-related development or progressive aggravation in mental disorders." (PMID 39058106, 2024).
pneumococcal infection (32 papers, 2007 to 2025). Infections with bacteria of the species streptococcus pneumoniae. "The pneumococcal infection was also associated with a significant increase in the expression of IL-6, TNF-α, CXCL1, and IFNγ in both groups and was significantly higher in the Zip8KO group when compared to the WT animals (p = 0.055)." (PMID 35162945, 2022). "Increased levels of TNF-α and IL-6 during pneumococcal infection are associated with severity of disease." (PMID 32318074, 2020). "The marked increase of IL-6 serum levels during the acute phase makes it a potential biomarker of pneumococcal infection among children with CAP." (PMID 40572766, 2025). "During pneumococcal infection in mice, IL-10 production is required to temper an excessive lung injury and to improve survival, while IL-27 in combination with IL-6 are involved in the ability of AMs to ty to promote Treg cell responses." (PMID 37958756, 2023). "IL-6 regulates HAMP expression during Influenza virus (PR8) or Streptococcus pneumoniae infections in mice and in human hepatocytes." (PMID 36675141, 2023). "Firstly, CXCL1 release, together with that of IL-1β and IL-6, plays a central role in Nφ mobilization from the bone marrow, in Nφ activation and in the control of bacterial dissemination in the lung after pneumococcal infection." (PMID 33042124, 2020). "Pneumococcal infection as well increased the mRNA expression levels of pro-inflammatory cytokines and chemokines, including Tnf-α, Il-6, Ccl3, and Cxcl10, which were equally reduced after treatment with Ac2-26." (PMID 33121515, 2020). "Our previous mathematical model predicted a synergistic role for IL-6 in aggravating the detrimental effect of IFN-γ in bacterial outgrowth following secondary pneumococcal infection in IAV infected mice." (PMID 31474978, 2019). "The massive production of cytokines such as TNF-α, IL-6, IL-12, CXCL1, and CXCL2 was a hallmark of the secondary pneumococcal infection after the flu." (PMID 29326698, 2017). "Early after pneumococcal infection, IL-6 is likely to play a predominantly protective role due to its immune-regulatory function in the feedback circuit of cytokines." (PMID 27872472, 2016). "IL-6 also protects host from pneumococcal infection through reducing the growth of pneumococci and prolonging survival." (PMID 26973817, 2016). "Interestingly, mice treated with D. pigrum 040417 had a differential production of IL-6 during pneumococcal infection compared with infected controls." (PMID 34207076, 2021). "Our data thus indicate that the improved production of IL-10, IL-27, and IL-6 by AMs of 040417-treated infant mice may play an important role in limiting inflammation during the pneumococcal infection by increasing the protective functions of Treg cells." (PMID 34207076, 2021). "Taken together, our results in principle confirm the predictions of our mathematical model, i.e., the potential of neutralizing IFN-γ alone and in combination with IL-6 for restoring anti-bacterial host defense in secondary pneumococcal infection following IAV infection." (PMID 31474978, 2019). "Increased IL-6 expression has been shown in a rat model of pneumocococal infection, and IL-6 GG homozygous patients (with increased IL-6 transcription and production) were less likely to develop extrapulmonary pneumococcal infection (as marker of impaired clearance of bacteria)." (PMID 17850649, 2007). "Interestingly, we found that the levels of NF-κB-related cytokines including TNF-α and IL-6 in the culture media were significantly increased in the early stage of pneumococcal infection, whereas cytokine levels were generally maintained during a 4-8 h infection or reduced at 8 h after infection." (PMID 26683708, 2015). "Pneumococcal infection can enhance the concentrations of TNF, IL-1β, IL-6, IFN-γ, and IL-10 in the respiratory tract and blood of immunocompetent well-nourished mice, while in protein-malnourished the levels of those immune mediators are significantly lower." (PMID 40507039, 2025).
pneumococcal infection (continued). "IL-10 modulates pulmonary inflammation that occurs in the context of pneumococcal infection by constraining the expression of TNF-α, IFN-γ, and IL-6." (PMID 29990318, 2018). "The pneumococcal infection resulted in a strong increase of GFAP and Itgam mRNA expression in the hippocampal formation and cortex of WT and IL-6−/− mice compared to uninfected WT." (PMID 27057100, 2016). "The results showed that by 24 h after pneumococcal infection there was a significant increase of protein production of CXCL1, IL-6, TNF-α, CXCL10 and G-CSF in virus/S." (PMID 24408967, 2014). "In addition, both immunomodulatory CRL431 and CRL1505 strains improved the production of TNF, IL-1β, IL-6, and IFN-γ in the respiratory tract compared to malnourished and BCD-treated mice, after the pneumococcal infection." (PMID 40507039, 2025). "Our results showed that the production of KC, MIP-2, IL-10, IL-6, and IL-1β did not significantly change when bacterial loads were similar in the lungs of dually infected mice and S. pneumoniae-infected mice after pneumococcal infection at 7 dpi." (PMID 33722928, 2021). "They only demonstrated that IL-6 levels under 12.5 pg/mL have a high negative predictive value for pneumococcal infection among these children." (PMID 32695814, 2020). "On the basis of existing knowledge of the biological function of the ICAM and IL-6 genes in the host response to pneumococcal infection, we conducted a pilot study to quantify ICAM and IL-6 gene expression in Malawian children presenting with invasive pneumococcal disease." (PMID 17850649, 2007). "Studies using naive mice have also shown elevated levels of IL-6, IL-1β, MCP-1, MIP-1, MIP-2 and KC in lung tissue starting at 24 hours post challenge in animals that do not control pneumococcal infection." (PMID 29360883, 2018). "In addition, the production of IL-10, IL-6, and TNF-α did not significantly change, notably in contrast to IL-1β, which was significantly enhanced after pneumococcal infection at 14 dpi in our study." (PMID 33722928, 2021).